MYBL2 (MYB proto-oncogene like 2)
Diseases named in the same sentence as MYBL2 in open-access papers (continued):
Sharing a sentence is not in itself a finding about the gene and the disease.
multiple myeloma (5 papers, 2022 to 2024). "Prognostic analysis of MYBL2 in myeloma using Kaplan−Meier database plotting tools revealed a correlation with reduced survival in myeloma patients." (PMID 39139556, 2024). "This analysis also extended our results into liquid tumors with MYBL2 expression being robustly prognostic in the most recalcitrant form of multiple myeloma, late relapse multiple myeloma (LRMM, >4 lines of prior therapy)." (PMID 36358918, 2022). "Overexpression of circ-MYBL2 in multiple myeloma cells downregulates the expression of proliferation-related oncogenes by increasing the binding of Cyclin F to MYBL2, which inhibits the activation and phosphorylation of MYBL2." (PMID 35387554, 2022). "Elevated expression of MYBL2 in multiple myeloma correlates with a poorer prognosis." (PMID 39139556, 2024). "In contrast, downregulation of circ-MYBL2 was observed in multiple myeloma." (PMID 35387554, 2022).
osteosarcoma (5 papers, 2020 to 2025). A usually aggressive malignant bone-forming mesenchymal neoplasm, predominantly affecting adolescents and young adults. "In July 2023, Qiu Xinzhu, He Hongbo and others systematically correlated MYBL2 with immune signatures in the pan-cancer tumor microenvironment, and used their risk score to predict the prognostic ability of osteosarcoma." (PMID 39445018, 2024). "They pointed out that MYBL2 regulates the proliferation development and immune infiltration of osteosarcoma and pan-cancer, and MYBL2 can be used as a potential marker in the osteosarcoma microenvironment to predict prognosis." (PMID 39445018, 2024). "As a prognostic indicator of unfavorable outcomes in osteosarcoma and a universal marker for immune infiltration across various cancers, MYBL2 exerts regulatory control over proliferation, tumor advancement, and immune cell infiltration within osteosarcoma and broader cancer contexts." (PMID 38994352, 2024).
renal carcinoma (4 papers, 2022 to 2025). A carcinoma arising from the epithelium of the renal parenchyma or the renal pelvis. "Cell cycle arrest and senescence is reported to be induced in MYBL2 or FOXM1 deficient cells, while overexpression of FOXM1b contributes to the pathogenesis of many cancers i.e., colorectal, nasopharyngeal and renal cancer." (PMID 35409296, 2022). "For instance, genes such as MYBL2, C7, FAM111B, LYVE, PKMYT, and HBB display comparable importance in classifying both breast and renal carcinomas." (PMID 39596491, 2024). "In contrast, high expression of FRZB, MYBL2, MYL2, NETO2, PLSCR4, and TES predicts an unfavorable outcome in endometrial, head and neck, liver, pancreatic, and renal cancer." (PMID 36497479, 2022).
breast tumors (3 papers, 2014 to 2022). "This upregulation of MYBL2 in breast tumorigenesis was substantiated by an analysis of mRNA expression data (RNAseqV2) for 1090 breast tumor samples and 112 normal samples as retrieved from The Cancer Genome Atlas (TCGA) project." (PMID 28276478, 2017). "Thus, our results, including cell-based and clinical analyses, supported the idea that MYBL2 promotes A3B induction in human breast tumors." (PMID 28276478, 2017).
clear cell renal carcinoma (3 papers, 2017 to 2024). A malignant epithelial neoplasm of the kidney characterized by the presence of lipid-containing clear cells within a vascular network. "In clear cell renal carcinoma, MYBL2 promotes malignant characteristics and impedes apoptosis through activation of the hedgehog signaling pathway." (PMID 38994352, 2024).
Fanconi anemia (3 papers, 2020 to 2025). Fanconi anemia (FA) is a hereditary DNA repair disorder characterized by progressive pancytopenia with bone marrow failure, variable congenital malformations and predisposition to develop hematological or solid tumors. "This occurs in part via a Wnt/β‐catenin pathway acting in part through MYBL2, that enhances the expression of genes involved in homologous recombination and Fanconi anemia pathways, including BRCA1, BRCA2 and multiple FANC genes." (PMID 33660437, 2021). "We found that MYBL2 High tumors lacked deleterious alterations in checkpoint, HR, or Fanconi Anemia (FA) repair pathways." (PMID 33489883, 2020).
meningioma (3 papers, 2020 to 2023). A generally slow growing tumor attached to the dura mater. "Our results were consistent with earlier studies that reported mutations in NF2, SMO, and AKT1 genes in atypical meningiomas, and we also observed mutations in MYBL2, a gene that was recently discovered." (PMID 32742192, 2020). "Elevated FOXM1 and MYBL2 is associated with more aggressive meningioma." (PMID 37860270, 2023). "The authors found increased expression of the DREAM complex partners FOXM1 and MYBL2 in those tumors compared to type B meningiomas, resulting in activation of the DREAM complex." (PMID 36937440, 2023). "In this study, the presence of AKT1 and SMO mutations along with mutated MYBL2, both in the NF2-mutant primary atypical meningioma tumor and the derived cell line, proved that the meningioma-derived primary cell line had retained the genetic signature of the original tumor." (PMID 32742192, 2020). "In meningioma, the alterations of the MYBL2 might be involved in cancer initiation and progression by affecting cell cycle progression, resistance to therapy and favoring metastatic spread." (PMID 32742192, 2020). "Similarly, identifying a common transcriptomic change across meningioma allows for treatments to be developed that could prevent or rapidly treat tumour recurrence (e.g. restricting MYBL2 or FOXM1 expression)." (PMID 37860270, 2023).
metastatic disease (3 papers, 2010 to 2025). "Higher MYBL2 expression was associated with a higher rate of relapse in localized disease and poorer overall survival in men with metastatic disease in the CHAARTED trial." (PMID 36087093, 2022). "This variability could be lost due to metastatic disease when losing portions of the Y chromosome with resultant in loss of KDM5D and fewer specimens may have KDM5D to regulate MYBL2." (PMID 36087093, 2022). "It is clear that nearest neighbors of MYBL2 (e.g CCNA2) also undergo increases in entropy, thus implicating larger gene modules, in this case a cell-cycle module, that are altered in metastatic disease." (PMID 20673354, 2010).
myelodysplastic syndrome (3 papers, 2018 to 2024). A clonal hematopoietic disorder characterized by dysplasia and ineffective hematopoiesis in one or more of the hematopoietic cell lines. "Previously, MYBL2 mRNA expression has been suggested as a biomarker to identify patients with myelodysplastic syndrome that would respond to genotoxic treatments." (PMID 39113611, 2024). "Low levels of MYBL2 in myelodysplastic syndrome (MDS) patients also preceded transcriptional deregulation of DNA repair genes." (PMID 33660437, 2021).
pancreatic cancer (3 papers, 2021 to 2024). "However, only the expression of the MYBL2 gene displayed a notable association with the grade and stage of pancreatic cancer." (PMID 38947375, 2024). "Consistent with this, PORCN inhibition decreased MYBL2 protein abundance in HPAF‐II pancreatic tumors." (PMID 33660437, 2021). "Indeed, in our pancreatic cancer transcriptomic dataset, both FOXM1 and MYBL2 were robustly Wnt‐activated." (PMID 33660437, 2021).
prostate tumors (3 papers, 2007 to 2025). "Importantly, MYBL2 was among these master regulators, and a recent report demonstrates MYBL2-expressing, stem-like prostate tumors may be susceptible to CDK2 inhibition." (PMID 40624104, 2025). "To explore the role of MYBL2 in advanced PCa progression, we first analyzed the MYBL2 expression profile in clinical prostatic tumors using publicly available GEO and TCGA data." (PMID 33897882, 2021). "However, the clinical significance and biological functions of MYBL2 in advanced PCa progression and the cross-talk between MYBL2 and YAP in prostate tumor cells require further investigation." (PMID 33897882, 2021).
cervical tumor (2 papers, 2022 to 2024). "Circ-MYBL2 reduces miR-361-3p expression via sponging to enhance lymph node metastasis in cervical tumors." (PMID 38733529, 2024). "Both proliferation and invasion of cervical tumor cells are enhanced by circ-MYBL2." (PMID 38733529, 2024).
cutaneous malignant melanoma (2 papers, 2022 to 2024). "Additionally, our study further elucidates the role of MYBL2 in promoting CDCA8 transcription and the role of MYBL2 as an oncogene in CDCA8-dependent cutaneous malignant melanoma." (PMID 38961953, 2024). "We proposed that CDCA8 may be transcriptionally controlled by MYBL2 in cutaneous malignant melanoma." (PMID 38961953, 2024). "We propose that suppressing MYBL2 expression to modulate and reduce CDCA8 levels may be a strategy for cutaneous malignant melanoma treatment." (PMID 38961953, 2024). "Herein, we hypothesized that MYBL2 may modulate CDCA8 expression and contribute to the development of cutaneous melanoma." (PMID 38961953, 2024). "However, whether MYBL2 and CDCA8 play a role in malignant melanoma of the skin has not been clarified." (PMID 38961953, 2024).
esophageal squamous cell carcinoma (2 papers, 2021 to 2022). Esophageal squamous cell carcinoma (ESCC) is a type of esophageal carcinoma (EC) that can affect any part of the esophagus, but is usually located in the upper or middle third. "The article found that MYBL2 was a downstream target of miR‐30c‐2‐3p and was highly expressed in LUAD tissues with the capable of predicting a poor prognosis, which was consistent with the studies in esophageal squamous cell carcinoma, HCC and pancreatic ductal carcinoma." (PMID 34631522, 2021).
Ewing sarcoma (2 papers, 2020 to 2023). A small round cell tumor that lacks morphologic, immunohistochemical, and electron microscopic evidence of neuroectodermal differentiation. "MYBL2 has been identified as a direct target of EWSR1::FLI1 with germline polymorphisms associated with activation in Ewing sarcoma and RRM2 overexpression is associated with poor prognosis Ewing sarcoma." (PMID 36793594, 2023). "For example, MYBL2 was recently found to promote progression of Ewing sarcoma." (PMID 32084007, 2020). "For example, EWSR1 fusion is common in Ewing sarcoma, and EWSR1-FLI1 regulates the expression of MYBL2." (PMID 32084007, 2020).
gallbladder cancer (2 papers, 2021 to 2022). "In the previous study, overexpression of MYBL2 has been found to be related to poor prognosis in various cancers, such as prostate and gallbladder cancer." (PMID 35991567, 2022).
invasive breast carcinoma (2 papers, 2021 to 2023). A carcinoma that infiltrates the breast parenchyma. "Similar to invasive breast carcinoma, high expression of MYBL2 was significantly associated with poorer overall survival in TCGA cases." (PMID 33747961, 2021). "Compared with other disease sites in the available PanCan TCGA studies, HGSOC had the third highest alteration frequency, surpassing that of invasive breast carcinoma, for which MYBL2 (encoding B-Myb) carries a clinically significant predictive value." (PMID 33747961, 2021). "Furthermore, the Kaplan–Meier dataset plotter was performed to reveal that high expression of MYBL2, HOXC13, and E2F8 had a poor RFS rate in invasive breast cancers." (PMID 36814821, 2023).
myeloid malignancies (2 papers, 2013 to 2022). "We conclude that downregulation of MYBL2 activity below levels predicted by classical haploinsufficiency underlies the clonal expansion of hematopoietic progenitors in a large fraction of human myeloid malignancies." (PMID 23878725, 2013). "MYBL2 expression levels in myeloid malignancy patients were less than 50% of those in healthy individuals." (PMID 36291764, 2022). "Surprisingly, MYBL2 levels were also reduced in myeloid malignancy patients who possessed two intact copies of chromosome 20, indicating that loss of a single copy represents only one mechanism to reduce MYBL2 expression, i.e., the ‘tip-of-the-iceberg’." (PMID 23878725, 2013). "Moreover, reducing the expression of MYBL2 in mice induced symptoms of myeloid malignancies in the animals." (PMID 36291764, 2022). "Our results implicating a transforming role for sub-haploinsufficient levels of MYBL2 build upon earlier studies implicating progressive inactivation of CTNNA1 and the graded reduction of PU.1 expression in the molecular pathogenesis of myeloid malignancies." (PMID 23878725, 2013).
pancreatic adenocarcinoma (2 papers, 2022). "Opposite roles of circular RNA MM-associated circular RNA (circ-MYBL2) have been observed in different malignancies, and its role in pancreatic adenocarcinoma (PA) is unknown." (PMID 35387554, 2022).
sarcoma (2 papers, 2022 to 2024). A usually aggressive malignant neoplasm of the soft tissue or bone. "In terms of gene signatures, an immune-related five-gene signature based on MYBL2, FBN2, TSPAN7, GCSH, and DDX39B is a prognostic biomarker for sarcoma patients." (PMID 38240704, 2024).
small cell lung carcinoma (2 papers, 2020 to 2022). Small cell lung cancer (SCLC) is a highly aggressive malignant neoplasm, accounting for 10-15% of lung cancer cases, characterized byrapid growth, and early metastasis.
uterine corpus endometrial carcinoma (2 papers, 2022 to 2025). A endometrial carcinoma (disease) that involves the body of uterus. "This study aimed to investigate the multifaceted roles of MYB Proto-Oncogene Like 2 (MYBL2) in uterine corpus endometrial carcinoma (UCEC)." (PMID 40432915, 2025).
Acute T-cell leukemia (1 paper, 2024). "Acute T-cell leukemia cells sensitive to vorinostat-induced cell death showed MYBL2 downregulation upon treatment, while resistant cells expressing the CDK inhibitor p16INK4A lost the ability to suppress MYBL2." (PMID 38835346, 2024).
astrocytoma (1 paper, 2025). "Many studies on MYBL2, E2F7, CCN4, and MET genes promote tumor progression by promoting tumor proliferation, differentiation, and migration, which may also contribute to the malignant progression of IDH-mutant astrocytoma." (PMID 41460424, 2025).
B cell lymphomas (1 paper, 2019). "In this way, we detected the induction of transcription factors genes implicated in B-cell differentiation and activation, PAX5 and IRF8 as well as of MYBL2, a transcription factor participating in cell cycle progression and recently described as a direct Notch1 target in B cell lymphomas." (PMID 31676012, 2019).
bladder (1 paper, 2019). "Our study suggests that circ_0006332 acts as a sponge for miR-143 and promotes high expression of MYBL2 that drives bladder tumorigenesis." (PMID 31756170, 2019).
breast adenocarcinoma (1 paper, 2020). "Notably, CENPA, FOXM1, and MYBL2 are also key regulators of cancer-specific enhancers in breast adenocarcinoma of the basal subtype, but they are associated with distinct sets of activated enhancers." (PMID 32925947, 2020). "In previous analyses, we found that FOXM1 and MYBL2 were activated in breast adenocarcinoma (BRCA)." (PMID 32925947, 2020).
cervical intraepithelial neoplasia (1 paper, 2025). "Additionally, elevated MYBL2 protein expression has been shown to serve as a predictive biomarker for progression in cervical intraepithelial neoplasia." (PMID 40508156, 2025).
colorectal adenoma (1 paper, 2021). An adenoma that arises from the colon or rectum. "As expected, the expression correlation between RRM2 and MYBL2 was significantly strengthened in the colorectal adenoma and carcinoma tissues accordingly." (PMID 34234118, 2021). "In comparison with adjacent noncancerous tissues, the mRNA expression levels of MYBL2 were increased both in colorectal adenomas and all stages of CRC in the TCGA and GEO cohorts." (PMID 34234118, 2021).
diabetes (1 paper, 2020). "Moreover, a new non-synonymous SNP R687C in exon 14 of MYBL2 was identified in a genome scan study in Ashkenazi patients with type 2 diabetes, suggesting a potential role of MYBL2 in diabetes." (PMID 33133095, 2020).
dysplasia (1 paper, 2013). A usually neoplastic transformation of the cell, associated with altered architectural tissue patterns. "The bone marrow of secondary recipients was also dominated by GFP+/Mybl2-RNAi cells and showed decreased levels of erythropoiesis as well as histologic evidence of a myeloproliferative disorder with dysplasia." (PMID 23878725, 2013).
ischemic stroke (1 paper, 2024). A stroke disorder caused by obstruction of blood flow to the brain, due to thrombotic (local blood clot formation) or embolic (due to a blood clot or other material traveling from another site) event. "Both ZNF385D and MYBL2 are amongst the hub genes identified to explain the impact of COVID-19 on ischemic stroke." (PMID 38674024, 2024).
malignant glioma (1 paper, 2022). A grade III or grade IV glioma arising from the central nervous system. "Given that we found EIF4EBP1 to be a target gene of the ETS1 and MYBL2 oncoproteins in malignant gliomas, 4EBP1 may possibly contribute to ETS1 and MYBL2 tumorigenic functions in these tumors." (PMID 35228525, 2022). "The molecular mechanisms underlying MYBL2 and ETS1 overexpression in malignant gliomas are to date unknown." (PMID 35228525, 2022). "Finally, by employing transient knock-down experiments to repress either of these transcription factors, we identified MYBL2 and ETS1 as the relevant transcriptional drivers of enhanced EIF4EBP1 expression in malignant glioma cells." (PMID 35228525, 2022).
medulloblastoma (1 paper, 2022). A malignant, invasive embryonal neoplasm arising from the cerebellum. "Recent studies have shown that MYBL2 was negatively regulated by mir-30b-5p in medulloblastoma." (PMID 35200555, 2022).
metastatic cancer (1 paper, 2024). A carcinoma which has spread from the original site of growth to another anatomic site. "One possible explanation could be that MYBL2 and FOXM1 might influence cancer cell survival through mechanisms other than cell cycle regulation, such as apoptosis or metabolic adaptation, which are critical for sustaining the growth and survival of metastatic cancer cells." (PMID 39518122, 2024).
metastatic melanoma (1 paper, 2022). A melanoma that has spread from its primary site to another anatomic site. "In the present study, we observed that MYBL2 was overexpressed in malignant and metastatic melanoma patient samples and that the high expression level of MYBL2 was significantly associated with poor prognosis." (PMID 35664780, 2022).
metastatic prostate carcinoma (1 paper, 2025). A carcinoma that arises from the prostate gland and has spread to other anatomic sites. "Elucidating the oncogenic role of MYBL2 may unveil potential therapeutic targets for metastatic prostate cancer (PCa)." (PMID 40092688, 2025).
peritoneal cancer (1 paper, 2016). A peritoneum cancer that is located in the inside of the abdomen. "Deregulation of the expression of BAG1, CCNB1, MKI67, and MYBL2 was documented in PC biopsies, suggesting that growth and cell proliferation pathways are disturbed, a feature of malignant transformation in ovarian and peritoneal cancer that has been widely documented in the literature." (PMID 27542596, 2016).
prostate adenocarcinoma (1 paper, 2025). "More significantly, our findings indicated a positive correlation between MYBL2 expression and tumor mutational burden (TMB), particularly in prostate adenocarcinoma (PRAD)." (PMID 40092688, 2025). "Furthermore, MYBL2 served as a predictive marker for increased tumor mutational burden (TMB) in patients with cancer, with this effect being particularly pronounced in prostate adenocarcinoma (PRAD)." (PMID 40092688, 2025).
squamous cell carcinoma (1 paper, 2024). A carcinoma arising from squamous epithelial cells. "In addition, in A431 human epidermoid carcinoma cells and Chinese hamster ovary cells, E2F1 bound to the MYBL2 promoter and activated its transcription." (PMID 39613162, 2024).